SGK1 (serum/glucocorticoid regulated kinase 1)
Diseases named in the same sentence as SGK1 in open-access papers (continued):
Sharing a sentence is not in itself a finding about the gene and the disease.
breast cancer (continued). "The main hypothesis is that the downregulation of GCR could alter SGK1 and Bcl-2 levels, which may contribute to the progression or aggression of breast cancer." (PMID 37370761, 2023). "SGK1 was originally cloned from rat mammary tumor cells stimulated by serum and glucocorticoids." (PMID 35106936, 2022). "In addition, previous studies also suggested SGK1 was important for breast cancer growth and resistance to PI3K inhibitors, indicating that targeting SGK1 would generate pleiotropic antitumor effects." (PMID 34272474, 2021). "We demonstrated that Dex could promote the migration of breast cancer cells through SGK1-CTGF signaling, and that ablation of SGK1 or CTGF reduced metastatic outgrowth and prolonged survival in mouse models." (PMID 34272474, 2021). "Our results have strengthened the concept that SGK1 might be a potential candidate to overcome chemotherapy-induced metastasis in breast cancer." (PMID 34272474, 2021). "Our present data provide new insights into Dex-induced breast cancer metastasis and indicate that SGK1 could be a candidate target for the treatment of breast cancer metastasis." (PMID 34272474, 2021). "Of note, opportunistic compensation of AKT and SGK1 has been characterized in breast cancer cells." (PMID 32901079, 2020). "Interestingly, SGK1 and SGK3 have also been linked to PI3K/AKT-targeted therapy resistance in breast cancer." (PMID 32630372, 2020). "Moreover, in hypoxic breast cancer cells, SGK1 expression was obviously stimulated to sustain cell survival." (PMID 33542904, 2020). "For example, SGK1 promotes resistance of breast cancer cells to Akt and PI3Kα-directed agents." (PMID 30655532, 2019). "However, a previous study shows that several Akt-inhibitor-sensitive breast cancer cells showed marked NDRG1 phosphorylation despite the low or undetectable level of SGK1 protein." (PMID 30811403, 2019). "Transcriptomic analysis of a number of breast cancer cell lines with different BYL719-resistance status pointed out to SGK1, since the phosphorylation levels of its target N-Myc Downstream Regulated 1 (phosphoNDRG1) were significantly elevated compared to total protein in resistant cell lines." (PMID 29064423, 2017). "Further, overexpression of SGK1 has been reported in multiple cancers, including breast cancer." (PMID 26219339, 2015). "Indeed, several reports have described the contribution of SGK1 and/or SGK3 to cancer progression, and a recent report identified a subset of breast-cancer cell lines that are intrinsically resistant to Akt inhibition due to constitutive upregulation of SGK1." (PMID 24558442, 2014). "Our main conclusion from the research undertaken in the present study is that elevated SGK1 might be deployed to predict resistance of breast-cancer-derived cells to Akt inhibitors." (PMID 23581296, 2013). "Indeed, one of the Akt-inhibitor-resistant breast cancer cell lines we have analysed (MDA-MB-157) displays low SGK1 levels and NDRG1 phosphorylation." (PMID 23581296, 2013). "SGK1 and Bcl-2 may play biological roles in breast cancer development and/or progression." (PMID 37370761, 2023). "Moreover, we observed an enriched binding of PR, estrogen receptor (ER), and p300 at the SGK1 genomic locus to enhance the expression of SGK1; this finding corroborates with previous analyses that progesterone alters the ER genomic activity in breast cancer." (PMID 37395734, 2023). "This recent study showed that this mutation leads to a non-canonic activation of SGK1 (serum/glucocorticoid-regulated kinase 1) which is implicated in various neoplasms (as breast cancer, hepatocellular carcinoma, glioblastoma, colorectal cancer and non-small cell lung cancer)." (PMID 35642047, 2022). "Furthermore, elevated SGK1 can predict for AKT inhibitor resistance in breast cancer cells." (PMID 32630372, 2020). "Therefore, β2M may promote the survival of tumor cells through the mTORC1/SGK1/Bcl-2 signaling pathway in ER+ breast cancer cells with HER2− (MCF-7 and T47D)." (PMID 30866857, 2019).
breast cancer (continued). "Thus, we asked whether NDRG1 could be regulated by AP-1 network genes in response to progesterone-induced activation of SGK1 in a similar manner in breast cancer cells." (PMID 30337371, 2018). "SGK1 is an AGC protein kinase of the SGK family and can be identified and characterized as a tumor-promoting candidate in several malignancies, including breast cancer, colorectal cancer, non-small cell lung cancer, as well as GC." (PMID 40500263, 2025). "Silencing SGK1, a kinase known to regulate NDRG1 phosphorylation, was also found to inhibit NDRG1 expression and increase breast cancer cell migration and invasion in vitro." (PMID 38611020, 2024). "We showed that the upregulation of SGK1 led to the activation of NDRG1, mediated by AP-1 network genes to inactivate AKT1, ERK1/2, and EGFR kinases, and thus, inhibit breast cancer cell invasion and migration." (PMID 37395734, 2023). "The cell culture experiments, using 21 breast cancer cell lines had shown that sensitivity of breast cancer cell lines to AKT inhibitors AZD5363 and MK-2206 correlates with SGK1 mRNA levels." (PMID 35625991, 2022). "The expression levels of β2M, HIF-1α, p-CREB, VEGF, p-SGK1, p-ERK1/2, and Bcl-2 were significantly higher in cancer tissues of patients with luminal A breast cancer compared to adjacent tissues (p < 0.05)." (PMID 30866857, 2019). "Co-phosphorylation analysis suggests strong correlation between the behaviour of SGK1 substrates and S330 in the ovarian cancer cell line while PRKACA annotated substrates track S330 more closely in the breast cancer models." (PMID 30811403, 2019). "SGK1, when overexpressed in PR-positive T47D and PR-negative MDA-MB-231 breast cancer cells, mimicked the effect of progesterone by up-regulating the expression of NDRG1, which in turn led to a significant reduction in cell migration and cell invasion." (PMID 30337371, 2018). "In breast cancer, it was recently shown that PDK1 inhibition was able to re-sensitize PIK3CA-mutant cells to PI3Kα inhibitors through suppression of SGK1 and reduction of mTORC1 activity." (PMID 29064423, 2017). "We observed an up-regulation of the expression of the SGK1 protein, regardless of the histological type, stage, or grade of breast cancer, indicating an oncogenic role of SGK1 early in tumorigenesis in breast cancer." (PMID 37370761, 2023). "Moreover, in a Src kinase -omics identification analysis of MCF10A breast cancer epithelial cells, it was found that ROR1 and SGK1 are located in different regulatory branches, thus suggesting an independent pathway as revealed by our study." (PMID 34272474, 2021). "In addition, analysis using the GSEA (Gene Set Enrichment Analysis) database revealed that the expression of SGK1 and CTGF was positively correlated in breast cancer (P < 0.001)." (PMID 34272474, 2021). "Based on the fact that both SGK1 and CTGF were involved in the process of Dex-induced breast cancer metastasis, we queried whether crosstalk exists between these two key genes." (PMID 34272474, 2021). "In PIK3CA mutant breast cancer cells, PDK1-SGK1 signaling has been shown to sustain AKT-independent mTORC1 activation to promote resistance to the p110α-isoform-specific PI3K inhibitor BLY719, and PDK1 or SGK1 blockade can restore BYL719 sensitivity." (PMID 32630372, 2020). "Moreover, SGK1 depletion prevented the dexamethasone-induced increase in SGK1 expression and the inhibitory effects of dexamethasone on paclitaxel-induced SEK1-JNK signaling and apoptosis in MDA-MB-231 breast cancer cells." (PMID 33542904, 2020).
breast cancer (continued). "Besides, GR-mediated Sgk1 activation suppressed tumor cell apoptosis in breast carcinoma cells and NDRG1 was reported to be induced by Sgk1 to inhibit apoptosis in ESCC tumor cells." (PMID 32106831, 2020). "Second, β2M inhibits CREB signaling and the expression of VEGF protein and activates ERK signaling, but does not affect HIF-1α and SGK1 signaling in ER− breast cancer cells with HER2−." (PMID 30866857, 2019). "Taken together, our results suggest that the SGK1/NDRG1 axis mediates regulation of activation of kinases involved in breast cancer cell migration, independent of their hormonal receptor status." (PMID 30337371, 2018). "We analyzed the basal mRNA expression of 27 breast cancer cell lines, previously characterized as sensitive or resistant to BYL719, and found that resistant cell lines had significantly higher levels of SGK1 mRNA compared with sensitive cells." (PMID 27451907, 2016). "We then explored whether SGK1 and pNDRG1 expression correlate with clinical outcome to PI3Kα inhibition by analyzing PIK3CA-mutant breast cancer samples from 18 patients treated with BYL719 in combination with an aromatase inhibitor (NCT01870505)." (PMID 27451907, 2016). "Consistent with this, extremely high doses of 100 μM EMD638683 are required to observe marginal reduction in NDRG1 phosphorylation in breast cancer cells that express high levels of SGK1 (Eeva Sommer, data not shown)." (PMID 27481935, 2016). "Treatment of breast cancer cell lines ZR‐75‐1 and CAMA‐1 that have low levels of SGK1 with structurally diverse Akt inhibitors (MK‐2206 and AZD5363) for 1 h inhibited phosphorylation of PRAS40 (Thr246, Akt‐specific substrate) as well as NDRG1 (Thr346, Akt and SGK substrate)." (PMID 27481935, 2016). "More recently, microarray analysis of dexamethasone-induced anti-apoptotic genes in breast cancer cells lines revealed MKP-1 and SGK-1 proteins to be of particular importance in GC-induced chemotherapy resistance in breast cancer, with glucocorticoid treatment up-regulating both of these genes." (PMID 24709697, 2013). "Not surprisingly then, SGK1 expression was found to be deregulated in several tumour types (up-regulated in breast cancers and down-regulated in prostate cancers and ovarian tumours)." (PMID 21079778, 2010). "On the other hand, targeting SGK1 with a small molecule (GSK650394) could inhibit dexamethasone-induced lung metastasis without affecting antitumor capacity, as demonstrated in a murine breast cancer model." (PMID 34868927, 2021). "Interestingly, breast cancer cell lines resistant to the AKT inhibitors capivasertib and MK-2206 express high levels of SGK1 and are sensitive to SGK knockdown (KD), while sustained AKT inhibition leads to increased SGK3 expression that can replace AKT-mediated activation of mTORC1." (PMID 33105713, 2020). "β2M has a different molecular regulatory mechanism between ER+ and ER− breast cancer with HER2−, and it may promote tumor survival through the SGK1/Bcl-2 signaling pathway in ER+ breast cancer with HER2− and has no regulatory effects on ER− breast cancer with HER2−." (PMID 30866857, 2019). "Thus, enhanced expression of SGK1 and NDRG1 could explain better survival of breast cancer patients." (PMID 30337371, 2018). "The stringent up-regulation of SGK1 in response to progesterone led to an activation of a tumor metastasis suppressor gene, NDRG1, via a set of AP-1 network genes to inactivate AKT1, ERK1/2, and EGFR kinases, impeding the invasion and migration of breast cancer cells." (PMID 30337371, 2018). "Interestingly, SGK1 activation (induction of p-SGK1 in response to progesterone) was found to be comparable in breast cancer cells, regardless of their PR status." (PMID 30337371, 2018). "However, SGK1 functions differ depending on the cell type and its overexpression has also been shown to promote cell proliferation and to dictate resistance to anti-AKT therapies in breast cancer cell lines." (PMID 28041796, 2017).
breast cancer (continued). "Thus, treatment with a GC alone or combined with chemotherapy led to an increased protein expression of SGK-1 and MKP-1 while specific inhibition of these molecules by small interfering RNA reversed the anti-apoptotic effects of GC treatment in breast cancer cells." (PMID 16539710, 2006). "Consequently, β2M may promote tumor survival through the SGK1/Bcl-2 signaling pathway in ER+ breast cancer with HER2− and have no regulatory effects in ER− breast cancer with HER2−." (PMID 30866857, 2019). "To establish whether there was a link between resistance to Akt inhibitors and SGK1 expression, we first compared the GI50 values mediated by the Akt inhibitor AZD5363 (that does not significantly inhibit SGK1) with relative SGK1 mRNA levels in 21 breast cancer cell lines." (PMID 23581296, 2013). "First, β2M activates SGK1 signaling and upregulates Bcl-2 expression, and do not affect HER2, HIF-1α, VEGF, and ERK signaling in ER+ breast cancer cells with HER2−." (PMID 30866857, 2019). "Our study suggests that SGK1 up-regulates the expression of NDRG1, with no significant change in phosphorylation of NDRG1 in breast cancer cells." (PMID 30337371, 2018). "We describe that SGK1 regulates the expression of NDRG1 via regulation of expression of EGR1, a transcription factor from the AP-1 network genes, in breast cancer independent of the PR status of cells." (PMID 30337371, 2018). "Taken together, the data suggest convergence of the dual mode of regulation at SGK1 in response to progesterone treatment, along with up-regulation of NDRG1 in multiple breast cancer cell lines independent of their PR status." (PMID 30337371, 2018). "In a reciprocal approach, depletion of SGK1 in T47D and MDA-MB-231 cells led to a decrease in expression of NDRG1 with an inverse effect observed on migration and invasion of the breast cancer cells, regardless of progesterone treatment." (PMID 30337371, 2018). "The molecular mechanisms of mitochondrial dysfunction in breast cancer are not entirely understood, and they might involve crosstalk between GCR, SGK1, and Bcl-2 via chronic stress and apoptosis pathways." (PMID 37370761, 2023). "This modulation may be mediated by the upregulation of the kinase gene SGK1, which activates the AP-1/NDRG1 axis in both progesterone receptor (PR)-positive and -negative breast cancer cells." (PMID 37395734, 2023). "SGK1 and GCR staining was not related to overall or breast cancer-specific survival." (PMID 37370761, 2023). "β2M may promote tumor survival through the SGK1/Bcl-2 signaling pathway in ER+ breast cancer with HER2− and have no regulatory effects on ER− breast cancer with HER2−." (PMID 30866857, 2019).
Hypertension (51 papers, 2009 to 2025). The presence of chronic increased pressure in the systemic arterial system. "Given that SGK1 has been implicated in renal sodium retention and associated with hypertension, these findings highlight the need for continued investigation into the potential roles of SGK2 in both placental function and maternal cardiovascular health." (PMID 41444673, 2025). "Hyperactivity of SGK1 has been linked not only to excessive epithelial sodium channel (ENaC) activity and hypertension, but also to increased SGLT1 activity, further linking its dysregulation to obesity and metabolic dysregulation." (PMID 40862720, 2025). "SGK1 is a glucocorticoid-induced kinase that stabilizes Na+ transporters and has been linked to hypertension in the kidney while potentially providing protection against ischemic injury in the brain through modulation of other ion channels." (PMID 38145287, 2024). "Observations indicating that gain-of-function mutations in SGK-1 in humans cause hypertension, insulin resistance, and obesity underscore the significance of SGK-1 in the pathophysiology." (PMID 36975891, 2023). "Excess salt has been linked to the development of inflammation and hypertension through upregulation of the salt-sensitive kinase, serum and glucocorticoid-regulated kinase 1 (SGK1)." (PMID 36951464, 2023). "Abnormal SGK1 expression has been implicated in the pathogenesis of various diseases including hypertension, diabetic neuropathy, metabolic syndrome, ischemia, and neurodegenerative diseases." (PMID 37371111, 2023). "Elevated aldosterone and insulin both increase glucocorticoid kinase-1 (SGK-1) activity, which promotes hypertension, IR, and obesity, increasing the risk of CVD." (PMID 38075069, 2023). "In the kidney, SGK1 has been implicated in high blood pressure, salt-sensitive hypertension, renal fibrosis, type 2 diabetes, and renal inflammation." (PMID 37371111, 2023). "Enhanced SGK1 expression and/or kinase activity have been linked to several diseases including: cardiac fibrosis, hypertension, diabetes, diabetic nephropathy, and the development of several human tumors." (PMID 34761560, 2022). "Zhang’s gene-based analyses declared that SGK1 gene was associated with risk of hypertension (P=7.4 × 10−3) in the Chinese Han population." (PMID 36305246, 2022). "In contrary, SGK1 deficiency prevents the occurrence of hypertension caused by a high-fat/high-fructose diet." (PMID 36305246, 2022). "Data from Caucasian volunteers who had participated in the International Hypertension Pathotype (HyperPath) group suggested that two SGK1 SNVs (rs2758151 and rs9402571) are linked with salt-sensitive HTN." (PMID 36176775, 2022). "Individuals with the SGK1 polymorphism were associated with moderately enhanced occurrence of hypertension, shortened QT interval in electrocardiograms, stroke, obesity and diabetes." (PMID 33195190, 2020). "Aldosterone stimulates the renal salt reabsorptions via MR-induced Sgk1 expression; whereas elevated MR-Sgk1 signaling was associated with the pathogenesis of kidney fibrosis and hypertension." (PMID 32410988, 2020). "A SGK1 gene variant (prevalence approx. 3-5% in Caucasians and approx. 10% in Africans) is associated with hypertension, stroke, obesity and type 2 diabetes." (PMID 31225494, 2018). "Excessive expression and activity of SGK-1 promotes vascular remodelling and macrophage activation which results in worsening of the pathophysiological processes associated with hypertension, diabetes, tumour growth and infertility." (PMID 28094006, 2017). "Candidate gene studies revealed that the SGK1 SNPs rs1057293 and rs1743966 were both associated with hypertension and ischemic stroke." (PMID 28515798, 2017). "Hence, dysregulated SGK1 has been associated with multiple diseases, such as hypertension, cancer, autoimmunity, and neurodegenerative disorders." (PMID 36457711, 2022).